SDC1 (syndecan 1)
Diseases named in the same sentence as SDC1 in open-access papers (continued):
Sharing a sentence is not in itself a finding about the gene and the disease.
breast carcinoma (continued). "Co-expression analysis and gain- or loss-of-function of PTK7 in TNBC cell lines revealed that PTK7 participates in EGFR/Akt signaling regulation and associated with extracellular matrix organization and migration genes in breast cancer, including COL1A1, FN1, WNT5B, MMP11, MMP14 and SDC1." (PMID 34367983, 2021). "For example, reduced expression of SDC1 could lead to advanced stages of gastric cancer and CRC, while increased expression could promote the growth and proliferation of pancreatic and breast cancers." (PMID 35087751, 2021). "Furthermore, SDC1 affects AKT and STAT3 signaling pathways activated by the EGF receptor in breast cancer stem cells from triple-negative breast cancer." (PMID 32916872, 2020). "Moreover, SCUBE2, TMEM26, and SMOC2 were validated as subtype-specific coding genes in luminal A breast cancer, CDK12 and SDC1 in HER2 breast cancer and PSAT1 in triple negative breast cancer in TCGA and GEO datasets." (PMID 31801944, 2019). "Our findings suggest a role for tumor Sdc-1 in modulating the polarization of Th cells within the tumor microenvironment of breast cancer dependent on the type the disease (non-IBC vs. IBC)." (PMID 31145753, 2019). "In contrast, a significantly positive correlation between expression of Sdc-1 and IL-4 (r = 0.554, P = 0.032), IL-17 (r = 0.7, P = 0.004), and Foxp3 (r = 0.539, P = 0.038) was evident in breast carcinoma tissues of non-IBC." (PMID 31145753, 2019). "We had demonstrated that miR-122-5p suppressed SDC1 expression and enhanced the mobility of MCF-7 breast cancer cells, we examined whether liver-derived exosomes containing miR-122-5p would affect the mobility of breast cancer cells." (PMID 29963269, 2018). "Another important study showed that SDC1-positive human mammary fibroblasts (HMF) induced extracellular matrix remodeling by promoting an aligned fiber architecture, which promoted directional migration and invasion of breast cancer cells." (PMID 30197623, 2018). "SDC1 expression did not change significantly in patients with breast cancer at different prechemotherapy stages, different BMN grades, or estrogen receptor (ER) ER+/ER– genotypes as revealed in GEO profiles GDS4056 and GDS4057." (PMID 29963269, 2018). "The equal overall epithelial Sdc1 expression in the primary IDC and ILC can be explained by the same origin of both histological types—the epithelium of the terminal ductal lobular unit (TDLU), from which most breast cancers originate." (PMID 30151336, 2018). "This is consistent with the prognostic value of Syndecan-1 in different cancer entities, including breast cancer and in line with the negative correlation between the ER, PR and the proportion of CD138-positive cells in ductal breast carcinoma in situ." (PMID 28270211, 2017). "Breast cancer patients with positive nodal status displayed elevated SDC1 mRNA than negative-nodal patients." (PMID 29340066, 2017). "We have shown previously that Sdc1 functions as a critical regulator during ECM production and that Sdc1-expressing human mammary fibroblasts which are frequently found in the stroma of human breast carcinomas give rise to an aligned, invasion-permissive ECM." (PMID 26909794, 2016). "Additional studies compared expression of SDC1 in breast cancer cases with and without distant organ metastasis." (PMID 26293675, 2015). "In addition, expression of SDC1 and SDC4 was correlated with the Ki-67 mitosis index, suggesting a role in breast cancer cell proliferation." (PMID 26293675, 2015). "In another line of studies on human breast carcinoma, SDC-1 ectodomain, but not SDC-4, regulates ανβ3 integrin–SDC signaling complex." (PMID 24551591, 2014). "Moreover, MT1-MMP-induced SDC-1 shedding inhibits cell migration in HEK293T cells and cell proliferation in T47D breast carcinoma cells." (PMID 24551591, 2014).
breast carcinoma (continued). "Thus, a new generation of bisphosphonate, zoledronate (zoledronic acid, Zometa), downregulates the expression levels of SDC1, SDC2, and GPC1 and upregulates the expression of SDC4 in breast cancer cells of low and high metastatic capability." (PMID 25140302, 2014). "Moreover shed SDC-1 inhibits alveolar epithelial wound healing, promotes fibrogenesis, and decreases invasion of TIMP-1-sensitive breast cancer cell invasion." (PMID 24551591, 2014). "In particular, shed SDC-1 expression is reported to regulate the expression of TIMP metallopeptidase inhibitor 1 (TIMP-1), urokinase plasminogen activator receptor (uPAR), and E-cadherin in breast cancer cells coordinating their invasiveness." (PMID 24551591, 2014). "Moreover increase of syndecan-1 impairs signaling of the MAPK pathway by inhibiting phosphorylation of MEK, Erk, and Bad, that results in apoptosis induction in breast cancer cells." (PMID 22811918, 2012). "Our previous in vitro studies have defined a novel pathway whereby n-3 PUFA-enriched LDL inhibits human breast cancer cell growth: the n-3 PUFA, DHA activates PPARγ which results in transcriptional up-regulation of the Sdc-1 target gene and the syndecan-1 (SDC-1) protein induces apoptosis." (PMID 21655218, 2011). "Both syndecan-1 and syndecan-4 are overexpressed in an estrogen receptor -negative, highly proliferative breast carcinoma subtype." (PMID 20398359, 2010). "Whatever the case, it is clear that the osteolytic phenotype of aggressive human breast cancer cells involves multiple factors, including, but not limited to, heparanase, syndecan-1, and IL-8." (PMID 20200931, 2010). "The impact of shed syndecan-1 on osteoclastogenesis is important because it provides a novel mechanism for the extensive osteolysis seen in many breast cancer patients." (PMID 20200931, 2010). "We have previously shown that SDC1 expression affects cancer stem cell-related pathway components, including IL-6/STAT3, Notch, and EGFR signaling pathways, in SUM-149 triple-negative inflammatory breast cancer cells, an aggressive and deadly form of breast cancer." (PMID 36980680, 2023). "Hence, further study is required to determine whether MMP1, CD24, SDC1, and SPP1 could be used as biomarkers or immune therapy targets in breast cancer." (PMID 35037689, 2022). "In our results, high expression of MMP1, CD24, SDC1, and SPP1 correlated to the development of breast cancer, worse OS and immune cell infiltration, indicating that MMP1, CD24, SDC1, and SPP1 might be as the potential prognostic biomarkers and immunotherapy targets for breast tumor." (PMID 35037689, 2022). "Moreover, the role of Sdc-1 in breast cancer angiogenesis has previously not been investigated using unbiased screening approaches." (PMID 34066023, 2021). "Overall, these data expand our previous findings of an Sdc-1-dependent modulation of a CSC phenotype in breast cancer cells via the IL6/STAT3-, Wnt- and Notch-pathways and suggest that Sdc-1 knockdown may induce differentiation of the CSC population, thus attenuating malignant properties." (PMID 34070901, 2021). "Interestingly, our qPCR data demonstrate a significantly negative correlation between expression of Sdc-1 and IL-4 (r = - 0.564, P = 0.028), IL-17 (r = - 0.571, P = 0.026), and Foxp3 (r = - 0.607, P = 0.016) in breast carcinoma tissues of IBC patients." (PMID 31145753, 2019). "Thus, we assume that syndecan-1 and IL-34 do not act in concert to regulate macrophages in breast cancer." (PMID 29796177, 2018). "Accordingly, n-3 PUFAs induced apoptosis in breast cancer cells in vitro and in a Fat-1 mice breast cancer model, by inhibition of the MEK/ERK/Bad signaling pathway; the inhibition was induced through the increased expression of the integral membrane protein syndecan-1 (SDC-1)." (PMID 26821053, 2016).
breast carcinoma (continued). "Additionally, SDC1 expression coordinates β-integrin dependent and interleukin-6 (IL-6) dependent cell functions, such as cell adhesion, migration, and resistance to irradiation, in MDA-MB-231 breast cancer cells." (PMID 25140302, 2014). "Thus, in estrogen receptor-negative and highly proliferative breast carcinoma subtypes, SDC1 and SDC4 were found to be overexpressed." (PMID 25140302, 2014). "When an additional breast cancer cell line, MCF-7, was analyzed for its cancer stem cell pool, Syndecan-1 depleted cells revealed 0.31% (±0.3%) SP cells compared to 0.68% (±0.5%) in the control-siRNA transfected cells, corresponding to a Syndecan-1-dependent relative decrease by >40% (P<0.01, n=4)." (PMID 24392029, 2013). "Upregulation of glypican-3 upon syndecan-1 overexpression may contribute to the negative effects seen on proliferation and shown to be proapoptotic in both breast cancer and mesothelioma cell lines." (PMID 23144729, 2012). "The objective of this study was to evaluate the potential of targeting CD138 by immuno-PET imaging and radioimmunotherapy (RIT) using the antihuman syndecan-1 B-B4 mAb radiolabeled with either 124I or 131I in nude mice engrafted with the triple-negative MDA-MB-468 breast cancer cell line." (PMID 22214534, 2011). "Therefore, elevated SDC1 levels in tumor cells might serve as a negative prognostic indicator for breast cancer and a potential therapeutic target, particularly in the Luminal subtype." (PMID 41364407, 2025). "A significant upregulation of syndecan-1 and a positive correlation with the expression of CD44, a marker of cancer stem cell (CSC) phenotype, have been documented in inflammatory breast cancer, a particularly aggressive BC subtype." (PMID 36088392, 2023). "Finally, since our results show differences depending on the type of cell line (Luminal MCF-7 and triple-negative/basal MDA-MB-231), we analyzed the differential expression of Sdc-1 in non-tumor, primary tumors and metastases tissues from breast cancer patients." (PMID 34070901, 2021). "In addition, there was a strong negative correlation between SDC1 expression and extracellular matrix proteins, suggesting that SDC1 promotes tumor progression by interacting with extracellular matrix components and impacting breast cancer tissue remodeling." (PMID 26293675, 2015). "Our results showed that MV-enriched EVs isolated from obese breast cancer patients with pLNM contained higher SDC2, but not SDC1 and SDC4, compared to those with nLNM." (PMID 40940401, 2025). "By contrast, non-neoplastic breast epithelium from patients with breast cancer showed clear glandular architecture with weak staining with MUC-1 and syndecan-1 antibodies." (PMID 28399903, 2017). "This study aimed to examine the expression patterns of SDC1, SDC2, and SDC4 in EVs isolated from peripheral blood of neoadjuvant chemotherapy-naïve obese breast cancer patients with negative LNM (nLNM) and positive LNM (pLNM) to discover their potential as new biomarkers for LNM." (PMID 40940401, 2025). "We believe that senescent CAFs with high expression of SDC1 weaken breast cancer cell invasion and metastasis and decrease cytokine secretion; according, patients in our TNBC cohort with negative expression SDC1 in CAFs had poor prognosis and low frequencies of TILs." (PMID 37069585, 2023). "While we previously demonstrated a moderate effect of Sdc-1 on MDA-MB-231 cell viability, we did not observe any impact on cell cycle progression under our experimental conditions, suggesting subtype-specific effects on breast cancer cell proliferation." (PMID 34070901, 2021). "Indeed, syndecan-1 and syndecan-4, two cell surface HSPG that have recently been characterized as markers of aggressiveness in breast carcinoma, are overexpressed in estrogen-negative and highly proliferative carcinomas of the mammary gland." (PMID 24083491, 2013).
breast carcinoma (continued). "While Sdc1 expression in stromal fibroblasts is not required for ECM production, its presence alters ECM architecture in vivo and in vitro, resulting in an aligned, parallel ECM fiber organization that promotes the directional migration and invasion of breast carcinoma cells." (PMID 26909794, 2016).
Sepsis (101 papers, 2011 to 2026). Sepsis is defined as life-threatening organ dysfunction caused by a dysregulated host response to infection. "Previous studies linked elevated plasma syndecan-1, an established biomarker of glycocalyx disruption, to mortality in sepsis." (PMID 41593637, 2026). "Syndecan-1 is a potential marker for monitoring endothelial injury and recovery from sepsis-associated DIC." (PMID 40740948, 2025). "Our findings suggest that serum syndecan-1 is a promising biomarker for evaluating vascular endothelial injury and predicting recovery in patients with sepsis-associated disseminated intravascular coagulation (DIC)." (PMID 40740948, 2025). "Clinically, vitamin C-treated patients with sepsis-associated ARDS exhibited attenuated syndecan-1 elevation and concurrent improvement in PaO2/FiO2 ratios at 48 h post-intervention." (PMID 41488104, 2025). "This study aimed to investigate the association between serum syndecan-1 levels and recovery from sepsis-associated DIC in patients treated with anticoagulants." (PMID 40740948, 2025). "Prior studies have linked high SDC1 levels to renal dysfunction in sepsis: in a meta-analysis of 11 studies, patients with AKI had significantly higher SDC1 levels compared to those without." (PMID 40806992, 2025). "The serum levels of shed soluble syndecan-1 and syndecan-4 have been proven to be associated with various diseases, such as sepsis, ischemia–reperfusion injury, multiple types of cancer, pneumonia, and heart failure." (PMID 41357480, 2025). "After removal of immunocompromised patients, syndecan-1 remained associated with sepsis-associated PARDS (p = 0.04)." (PMID 37670670, 2024). "Several functional proteins, such as syndecan-1 and VE-cadherin, have been proposed as diagnostic and prognostic markers for sepsis due to their roles in regulating endothelial hyperpermeability." (PMID 38921594, 2024). "Plasma syndecan-1 concentration was significantly higher in children with sepsis-associated PARDS (median 146 ng/mL [IQR 32-315] vs 8 [IQR 8-50], p = 0.01) compared with patients without PARDS." (PMID 37670670, 2024). "For instance, in patients with sepsis caused by pneumonia, the concentration of plasma syndecan-1 increases over time, and the syndecan-1 is the only EG biomarker that is moderately correlated with inflammation." (PMID 37905167, 2023). "Increased shedding of syndecan-1 has been linked to higher disease severity in patients with sepsis." (PMID 35660785, 2022). "Syndecan-1 and sTM levels were positively associated with organ damage in patients with sepsis and septic shock." (PMID 36536028, 2022). "Studies have demonstrated that syndecan-1 shedding is associated with both sepsis presence and severity." (PMID 36536028, 2022). "Syndecan-1 and sTM are also strongly associated with organ (liver and renal) failure in critically ill patients with sepsis." (PMID 36341368, 2022). "Syndecan-1 and cfDNA signal pathophysiological processes that lead to vascular injury in sepsis-associated ARDS." (PMID 36297099, 2022). "Serum syndecan-1 is a known indicator of vascular endothelial damage that correlates with coagulation disorders associated with sepsis prognoses, such as persistent thrombocytopenia and disseminated intravascular coagulation (DIC)." (PMID 36278212, 2022). "Endothelial injury induces coagulation abnormalities during sepsis; therefore, we assessed the association between serum syndecan-1 and sTM levels and coagulation function parameters." (PMID 36536028, 2022). "Serum syndecan-1 and sTM levels were associated with organ dysfunction severity in septic patients, and both were good predictors for early identification of sepsis, particularly in patients undergoing septic shock." (PMID 36536028, 2022). "HDIVC treatment reduced 48 h cfDNA and syndecan-1 plasma levels in subjects with sepsis-associated ARDS." (PMID 36297099, 2022).
Sepsis (continued). "Several clinical studies have demonstrated elevated circulating levels of syndecan-1 as a marker of glycocalyx degradation in sepsis and are associated with organ dysfunction and mortality." (PMID 36119052, 2022). "This is consistent with previous studies showing that elevated syndecan-1 levels were associated with higher incidence of acute kidney injury in patients with severe trauma or sepsis." (PMID 34557532, 2021). "Our findings are consistent with previous studies showing that syndecan-1 levels were associated with coagulation failure in patients with sepsis." (PMID 34557532, 2021). "In the comparison of sepsis and septic shock, the number of biomarkers of endothelial dysfunction independently associated with septic shock dropped to four (SDC1, MR‐ProADM, THBD and ANGPT2)." (PMID 32073224, 2020). "Despite an increase of THBD in serum is associated with poorer outcome in sepsis, its circulating form as well as that of SDC1 reduces IL-6 expression, thereby serving to control an inflammatory response and preventing overwhelming immune reactions." (PMID 31396019, 2019). "The following paragraph aims to discuss the potential of the newly investigated but promising markers of endothelial damage, such as syndecan-1, heparan sulfates, heparanase, endocan, and angiopoietins as diagnostic tools in sepsis." (PMID 27699168, 2016). "Additionally, in patients with DIC associated with sepsis, serum syndecan-1 has been reported to correlate with DIC score." (PMID 40740948, 2025). "Incorporating syndecan-1 into clinical decision-making could improve the management of sepsis-associated DIC." (PMID 40740948, 2025). "Taken together, these results suggest that EGCX degradation as reflected by increased concentrations of highly sulfated HS disaccharides and syndecan-1 may be in part associated with the sepsis-associated PARDS pathobiology." (PMID 37670670, 2024). "We similarly observed higher circulating levels of syndecan-1 in sepsis-associated PARDS patients." (PMID 37670670, 2024). "Endogenous norepinephrine levels have been correlated with plasma syndecan-1 levels; however, this has been in the setting of sepsis with concurrent thromboinflammation, which may cause direct glycocalyx damage." (PMID 38658435, 2024). "In conclusion, our data suggest that SDC1 predicts prognosis in children with septic shock and sulodexide may have therapeutic potential for the treatment of sepsis-associated endothelial dysfunction." (PMID 37614234, 2023). "Plasma levels of syndecan-1 are associated with neutrophil activation and may reflect the degree of endothelial damage in patients with sepsis." (PMID 36675479, 2023). "Importantly, in patients with severe sepsis, decreased plasma levels of protein C and increased syndecan-1, which characterize endothelial damage, were associated with whole blood hypocoaguability in the context of DIC, as measured by thromboelastography." (PMID 37081895, 2023). "Therefore, we aimed to investigate the role of glycocalyx degradation by measuringserum syndecan-1 levels in pediatric sepsis and its association with sepsisseverity." (PMID 35081239, 2022). "A growing body of evidence indicates that SDC1 is released into the circulation in response to endothelial injury and elevated levels of serum SDC1 have been detected in patients with severe sepsis and have been associated with adverse clinical outcomes in patients with ischemic heart failure." (PMID 33668381, 2021). "In the present study, by analyzing a cohort of patients with suspected sepsis, we show that elevated circulating syndecan-1 may be associated with refractory thrombocytopenia during the first week of ICU stay." (PMID 34557532, 2021). "Furthermore, increased levels of SDC-1 were found to be associated with the development of DIC in sepsis patients." (PMID 31091226, 2019). "Studies demonstrate that syndecan-1 shedding is associated with both sepsis presence and severity." (PMID 30654825, 2019).